TNF (tumor necrosis factor)
Diseases named in the same sentence as TNF in open-access papers (continued):
Sharing a sentence is not in itself a finding about the gene and the disease.
diabetes (continued). "Os níveis séricos de IL1-β e TNF-α aumentaram significativamente no grupo diabético em comparação com o grupo controle nos dias 14 e 28 após a indução do diabetes (p<0,05) ( Tabelas 4 e 5 )." (PMID 34709299, 2021). "Our results suggest a mechanism of action of LPLI, where it could efficiently down-regulate diabetes-induced HMGB1 and TNF-α expression." (PMID 32750068, 2020). "Diabetes, impaired fasting glucose, HbA1c, hypertension, male sex, BMI, cTnT, CACS, WBC count, the number of all leukocyte types analyzed, and the levels of CRP, IL‐6, and TNF‐α were reproducibly, positively correlated with the QRS‐T angles." (PMID 32638456, 2020). "In this study, we investigated the analgesic effect of the combination of B1/B6/B12 (VBC) and its effects on the expression of P2X3 and TRPV1 receptors in DRG neurons and the inflammatory cytokines IL-1β, TNF-α, and NGF in the spinal cord in STZ-induced diabetic rats." (PMID 32104520, 2020). "Analysis of systemic inflammation found that TNFα level was likely to be higher in COPD patients with concomitant type 2 diabetes mellitus, regardless of genotype." (PMID 33072207, 2020). "Consistently, apoptosis of ECs, pericytes, and neurons was inhibited in TNF-α knockout mouse models with or without diabetes." (PMID 33013692, 2020). "The graphs detail all significant correlation found between the parameters, such as blood glucose levels and LTB4 (r = 0.5), as well as TNF-α (r = 0.8) regardless of diabetes status in subjects with CL." (PMID 32525457, 2020). "Accumulating evidence suggests that DR exhibits characteristics of chronic inflammation, as multiple pro-inflammatory factors such as tumor necrosis factor-α (TNF-α), intercellular cell adhesion molecule-1 (ICAM-1), and VEGF are overexpressed in the diabetic retina." (PMID 33291567, 2020). "In T1DM patients, higher adiponectin and TNF-α values were significantly correlated with younger age at onset of diabetes and they also showed significant negative correlations with age at onset of the autoimmune disease and HDL-cholesterol." (PMID 33202729, 2020). "Systemic and local inflammation (TNFα, IL-1β, CD68) were increased with diabetes." (PMID 32153425, 2020). "In our study, there was an upregulation of IL-6 and TNF-α in CRC animals with or without diabetes induction in the CRC and DCRC groups." (PMID 32664279, 2020). "Inflammation is one of the contributing factors in developing diabetes as demonstrated by higher levels of SAA and several other inflammatory markers such as TNF, C-reactive protein (CRP), and MCP-1 that parallel increased urinary albumin secretion in such subjects." (PMID 32075280, 2020). "Decreased GSK3β-Ser9 phosphorylation, increased TNF, IL-6, COX-2, and iNOS expression, and the abolishment of these effects by SB216763 can also be observed in the hippocampi of rats with diabetes induced by a combination of a high-fat diet and low streptozotocin concentrations." (PMID 32231133, 2020). "In addition, increased levels of inflammatory cytokines, such as interleukin (IL)-1, IL-6, and tumor necrosis factor alpha (TNF-α), are observed in diabetes but are also found in AD patients." (PMID 30845785, 2019). "Interestingly, SAR131675 treatment significantly lowered diabetes-induced systemic inflammation as indicated by decreased circulating MCP-1 and TNF-α levels in db/db mice." (PMID 30833548, 2019). "These time-course analyses show that fenoldopam inhibited and did not merely delay hyperglycemia or TNF production in endotoxemic mice with diabetes." (PMID 30700738, 2019). "While at the late phase of diabetes (i.e., 5 weeks), the protein expression of both CXCR4 and TNF-α all significantly increased in the spinal cord and in the DRG, which corresponds to a significant reduction of the paw withdrawal threshold and latency at 5 weeks of diabetes." (PMID 31001066, 2019).
diabetes (continued). "By contrast, CXCR4 and TNF-α in the spinal cord dorsal horn did not significantly increase at 2 weeks of diabetes while both were significantly upregulated at 5 weeks of diabetes." (PMID 31001066, 2019). "Furthermore, in the STZ model of diabetes in rats, increased expression of TNF-α, IFN-γ, and ROS-producing enzymes was normalized upon multiple antioxidant therapy, further strengthening the connection between diabetes-induced vascular damage and inflammation." (PMID 31341533, 2019). "Long‐term diabetes significantly increased plasma levels of TNF‐α, IL‐1 β and IL‐6 in diabetic rats without daily oral kirenol administration." (PMID 31565849, 2019). "The protein expressions of both CXCR4 and TNF-α were significantly increased early at 2 weeks of diabetes as compared to the control, and the DRG TNF-α and CXCR4 protein expression maintained significantly increased by 5 weeks of diabetes (P < 0.05, diabetes vs. control)." (PMID 31001066, 2019). "Among individuals with peri-implantitis, those having diabetes show an overproduction of multiple peri-implant fluid pro-inflammatory cytokines; IL-1, IL-6, IL-8, TNF-alpha, chemokine receptors CCR5 and CXR3, where the severity of dysregulation appears to be worsen with poor diabetes control." (PMID 31275749, 2019). "Behavior and conditions such as cigarette smoking, diabetes, HIV, end-stage renal disease (ESRD), and use of tumor necrosis factor (TNF)-alpha inhibitor medications or post-transplant immunosuppressive drugs have been found to increase an individual’s risk of reactivation by two to 25-fold." (PMID 30964878, 2019). "Regardless of the infection, our results indicate that diabetes exacerbates both hyperglycemic and TNF responses to bacterial endotoxin." (PMID 29780390, 2018). "When compared with the remaining participants, subjects who died during follow-up were older, more frequently men, had a higher prevalence of smoking habit and previous coronary artery disease but a similar rate of diabetes, eGFR and equivalent BMI, lipid profile, high-sensitivity CRP and TNF-α." (PMID 30271669, 2018). "Increases in inflammatory cytokines in diabetes promote tumour development, which include interleukin-6 (IL-6), monocyte chemoattractant protein, plasminogen activator inhibitor-1 (PAI-1), adiponectin, leptin, and tumor necrosis factor-alpha." (PMID 30271790, 2018). "Indeed, HSP60 levels were increased in the diabetes group together with an increase in HSP72 levels, whereas clear decreases in IL-6 and TNF-α levels were noted in this group." (PMID 29467719, 2018). "People with DM and periodontitis usually have elevated circulating proinflammatory mediators, like TNF-α, IL-6, CRP, and reactive oxygen species (ROS) that can interfere with diabetes metabolic control and may act synergistically in worsening cardiovascular complications in diabetes." (PMID 30356347, 2018). "It has been reported that CD4+ T cells are required for the initiation of diabetes and that the Th1 cytokines IFN-γ and TNF-α may contribute to islet β cell death." (PMID 29844327, 2018). "Our results show that diabetes increases serum glucose levels and induces hyperglycemia, but not detectable serum TNF levels by itself before the septic challenge." (PMID 29780390, 2018). "Thought ANG did not reproduce C/TNF-CM impact on beta-cells, it remains an interesting myokine that promote beta-cell replication during diabetes etiology." (PMID 29968746, 2018). "Interestingly, with ANOVA analysis, the exercise significantly increased circulating inflammatory markers (IL-1β, IL-6, TNF-α, and IL-10) and decreased WBC, while diabetes displayed significant effect on HR and TNF-α." (PMID 29467719, 2018). "We observed a significant decrease in the levels of TNF-α, IFN-γ, IL-12, and IL-6 in the baseline plasma samples from individuals with T2DM indicating a systemic downregulation in the cytokine levels among uncontrolled diabetes." (PMID 30258443, 2018).
diabetes (continued). "The level of TNF-α was increased with diabetes, but was not statistically significant in this experiment (p = 0.06)." (PMID 29453337, 2018). "Therefore, bosentan by inhibiting the upregulation of both TNF- α and VEGF would also play a significant role in preventing the hyperpermeability induced by diabetes." (PMID 30428543, 2018). "In addition, HLF decreased MDA level and enhanced SOD activities, inhibited TNF-α expression, and downregulated PKC-α mRNA, PKC-α, and NF-κB which were induced by diabetes." (PMID 29234372, 2017). "TNF-α level may play an important role and many factors may contribute to the serum TNF-α level in diabetes." (PMID 28426801, 2017). "Animal studies showed that prolonged healing of peptic ulcer in diabetic rats was associated with increased gastric mucosal expression and release of TNF-α and IL-1β, evidenced that amplification of local inflammation is also responsible for delayed healing process of PUD in diabetes." (PMID 29095895, 2017). "The pathophysiological link between COPD and diabetes is not entirely understood, although thought to involve systemic inflammation with central roles for IL-6 and TNF-α." (PMID 29165119, 2017). "Macrophages, by the release of proinflammatory cytokines (e.g., TNF-α, IL-6, and IL-1β), aggravate inflammation, which may be explained by the increased GLU activity in the STZ-induced diabetes." (PMID 29464184, 2017). "However, in the context of diabetes, the expression of REG3A was impaired in skin wounds and SHP-1 was observed to be diminished in parallel, thus leading to excessive production of TNF-α and IL-6 and delayed wound healing." (PMID 27830702, 2016). "Significant interaction effect of diabetes and DOX was observed for TNFα (P = 0.038)." (PMID 27512375, 2016). "Diabetes, especially Type 2 DM, leads to diabetic liver diseases, mostly common for NAFLD, by the mechanisms involving IR, oxidative stress, endoplastic reticulum stress, cytokines such as TNF‐α, etc.." (PMID 26645107, 2016). "Moreover, we observed that the induction of retinal CAS-3, TNF-α, MMP-2, and MMP-9 expressions by diabetes was inhibited by NXT treatment, suggesting an antiapoptotic and anti-inflammatory effects of NXT." (PMID 25821481, 2015). "No changes in plasma levels of OPN, IL-10, TNFα, IL-12p70, IL-1β, IL-6, and KC were observed in response to diabetes or NFAT inhibition; however plasma IFN-γ was reduced in diabetic animals that had been treated with A-285222." (PMID 25918731, 2015). "We found that the circulating proinflammatory cytokines IL-6, TNF-α and IL-Iβ, but not IFN-γ, were significantly elevated in the SENP1-deficient mice before the onset of diabetes at the age of 7 weeks." (PMID 26596471, 2015). "Therefore, the objective of this study was to investigate the relationship between the serum levels of leptin, TNF-α, and SAA in diabetes mellitus type 2 with nutritional status of vitamins E and C." (PMID 26693410, 2015). "The present clinical trial study was designed to assess the effect of topical application of melatonin on serum levels of tumor necrosis factor-alpha (TNF-α), interleukin-6 (IL-6) and C-reactive protein (CRP) in patients with diabetes and periodontal disease in comparison with healthy controls." (PMID 26644840, 2015). "Hence, a cross-sectional study was conducted to determine the effect of topical melatonin application on serum TNF-α, IL-6 and CRP concentrations in patients with diabetes and periodontal disease and in a control group of healthy subjects." (PMID 26644840, 2015). "In patients with DKD, serum IL-18 and TNF-α levels were higher in patients with diabetes than nondiabetic controls." (PMID 26064987, 2015). "Our results showed that both ascorbic acid and alpha-tocopherol could induce significant anti-inflammatory effects by decreasing the level of inflammatory factors such as TNF-α, SAA, and hs-CRP in diabetes mellitus type 2 patients." (PMID 26693410, 2015).
diabetes (continued). "There were no other significant relationships between cEPCs, cECs and TNF-α and participant characteristics (VO2peak, BMI, age and duration of diabetes) in either the control or Type 1 diabetes group." (PMID 26044827, 2015). "Previous reports showed that TNF-α administration in older mice prevented autoimmune diabetes in NOD mice and that TNF-α expression from a young age in TNF-α transgenic NOD mice accelerated diabetes progression." (PMID 25343451, 2014). "The mechanism of the inflammatory response leading to diabetes is not fully described, while accumulating data support that the lack of TNF-α or inhibiting its receptor induces the increased sensitivity of insulin." (PMID 24995360, 2014). "We examined nitric oxide (NO), IL-6, and TNF-α secretion from cultured palmitate-stimulated PBMNCs or in the plasma from type 2 diabetes mellitus (T2MD) patients or nondiabetic (ND) controls." (PMID 24803982, 2014). "Diabetes had no impact on the levels of cytokines produced by non-stimulated splenocytes, but resulted in significantly increased levels of TNF-α in cells stimulated with anti-CD3/CD28 beads." (PMID 23755169, 2014). "Furthermore, macrophages from mice with streptozotocin- (STZ-) induced diabetes display a dysfunctional phenotype, reduced CD86 expression, and proinflammatory cytokines such as TNF-α and IL-6 production but enhanced nitric oxide (NO) secretion." (PMID 24899891, 2014). "The ischemia-induced upregulation of those cytokines was markedly accelerated by diabetes: the diabetic control group showed a 15.9- and 21.0-fold increase in IL-1β and TNF-α expression, respectively, compared with the nondiabetic control group." (PMID 24739976, 2014). "Combined with greater IFN-γ and TNF-α production and enhanced cytolytic function, DC vaccination augmented CTL functional responses, compared to vaccination with peptide plus adjuvant, and promoted sufficient tissue destruction to result in diabetes." (PMID 24647761, 2014). "Diabetes significantly increased the retinal expressions of iNOS by 40%, IL-6 by 60%, and TNF-α by 35% as compared to nondiabetic rat retinas." (PMID 23671886, 2013). "In addition, we also demonstrated here that inhibition of ERK1/2 by U0126 significantly ameliorates diabetes-induced upregulation of iNOS, IL6, and TNF-α in the retina." (PMID 23671886, 2013). "The present study evaluates the effects of extract of Musa sapientum fruit (MSE) on ulcer index, blood glucose level and gastric mucosal cytokines, TNF-α and IL-1β and growth factor, TGF-α (affected in diabetes and chronic ulcer) in acetic acid (AA)-induced gastric ulcer (GU) in diabetic (DR) rat." (PMID 24192345, 2013). "Various studies have demonstrated that inhibition of pro-inflammatory cytokines (such as IL-1β, TNF-α, and VEGF), chemokines (such as MCP-1), or adhesion molecules (such as ICAM-1) can reduce diabetes-induced leukostasis, degeneration of retinal capillaries, or BRB breakdown." (PMID 23662142, 2013). "In insulin dependent diabetes mellitus (IDDM) various agents like interleukin-1 beta, interferon gamma, tumor necrosis factor alpha, alloxan and streptozotocin - could operate by forming free radicals that could attack the mitochondrial genome." (PMID 24250450, 2012). "Although this has not been completely defined, TNF-α seems to be the marker of “demetabolism” and maternal glycemic control in pregnancies that are complicated by type-2 diabetes mellitus and GDM." (PMID 22462002, 2012). "At variance with IL-1β, the retinal expression of IL-6 and TNF-α was not changed in diabetes at any of the time points tested." (PMID 22615852, 2012). "Prior to surgery, the serum levels of TNF-α were also higher in the participants with T2DM (19.36±6.34 pg/ml) than in those without diabetes (11.68±1.67 pg/ml)." (PMID 23119124, 2012). "Our protocol for strict diabetes control, a protocol not used in the previous study, was crucial to success as an adjunct to anti-TNF-α treatment." (PMID 22606220, 2012).
diabetes (continued). "TNF-α has previously been shown to induce at early at 1-2 weeks of STZ-induced diabetic rat retinas and then suppresses until late stages of diabetes duration where it may play a critical role in retinal inflammation and BRB breakdown." (PMID 22474421, 2012). "Then, the aim of this study was to investigate the possible microbiological changes and the spatial distribution and the number of immunostained cells to RAGE, TNF-alpha, IL-1beta, IL-6, RANKL and MMP-2, and MMP-9, in periodontal tissue after diabetes induction." (PMID 22611374, 2012). "The merging of the three significantly effected networks generated a complex network with regulatory hubs formed by inflammation related genes (e.g. TNF-α, NF-κB), kinases (e.g. AKT, PI-3 kinase), and transcriptional regulators (HNF4A, EGR1, Jnk) as well as diabetes related genes (Insulin, Ins1)." (PMID 22606220, 2012). "In obese individuals with the metabolic syndrome or with type 2 diabetes mellitus anti-TNFα failed to improve IR." (PMID 22765047, 2012). "In addition, supplementation with α-tocopherol resulted in decreased circulating IL-1β, IL-6, TNF-α, and CRP in individuals with diabetes." (PMID 23158971, 2012). "A further role of tumor necrosis factor-alpha inhibitors in the glycemic equilibrium warrants larger controlled trials in patients with and those without a history of diabetes." (PMID 22234148, 2012). "Elisa analysis demonstrated that diabetes increased the levels of left ventricular IL-6, IL-1α and tumor necrosis factor-α (TNF-α) as compared with the non-diabetic group." (PMID 22432030, 2012). "It is possible that, in diabetes, the cardiac origin of APN may play an important role in regulating systemic TNF-α." (PMID 21912612, 2011). "While the mechanism of action for isoproterenol has not been established, it was noted that diabetes increased tumor necrosis factor (TNF)α levels, which were reduced with the β-adrenergic receptor agonists." (PMID 21850156, 2011). "Further, lack of TNFα prevented the up-regulation of IL-6 and IL-1β mRNA otherwise observed in wt mice in response to diabetes." (PMID 20856927, 2010). "As a complementary approach to evaluate a potential endothelial dysfunction in response to diabetes, the expression of VCAM-1, ICAM-1, P-selectin and E-selectin mRNA was measured in intact retinas of wt, ApoE−/−, TNFα−/− and ApoE−/−/TNFα−/− mice by real time RT-PCR." (PMID 20856927, 2010). "Biological dysfunctions, found in diabetes, obesity, and the metabolic syndrome include, among others, increases in the circulating levels of metabolites, such as FFA and triglycerides, and cytokines such as TNF-α and IL-6." (PMID 20671994, 2010). "In short-term studies, Long-Evans rats with streptozotocin–induced diabetes were treated with or without the TNF-α inhibitor, etanercept." (PMID 19641635, 2009). "In a few studies published in recent years authors reported detectable TNF-α in the serum of children with long-standing diabetes, however these patients had no concomitantdiabetic complications." (PMID 17641733, 2007). "In vivo, Pn@Janus TPP implantation markedly enhanced alveolar bone regeneration in a diabetic rat periodontitis model, restored periodontal architecture, and reduced the expression of key pro-inflammatory cytokines (IL-6, TNF-α, iNOS, IL-1β), without inducing systemic toxicity." (PMID 41704297, 2026). "It is plausible that both our diabetic and non-diabetic cancer patients had high IL-6/TNF due to cancer; the people with diabetes might have had slightly higher levels, but all above a threshold that predisposes to depression." (PMID 41149069, 2025). "The ten important active constituents were chosen for molecular docking verification with the key targets TNF, AKT1, EGFR, and GSK3β (the core intersection target of the PPI network and Component-pathway-target network), which are considered potential targets in the treatment of diabetes." (PMID 40076380, 2025).